WT1 (WT1 transcription factor)
Diseases named in the same sentence as WT1 in open-access papers (continued):
Sharing a sentence is not in itself a finding about the gene and the disease.
breast carcinoma (97 papers, 2004 to 2025). "The WT1 protein was overexpressed in > 90% of breast cancers, and the 36–38 kDa isoform of WT1 was associated with estrogen receptor deletion in advanced breast cancers." (PMID 36829196, 2023). "In breast cancer, WT1 controls the expression of genes encoding components of the insulin-like growth factor and transforming growth factor β signaling systems that are important for growth and differentiation of the mammary gland." (PMID 35495123, 2022). "On the other hand, a high expression of WT1 in breast cancer is clinically associated to increased malignancy, bad prognosis, lower responsivity to therapies and to a mesenchymal phenotype." (PMID 33452364, 2021). "Associations between WT1 methylation and the risk of luminal subtypes of breast cancer and between CA10 methylation and the risk of luminal B subtype breast cancer were also observed." (PMID 32736539, 2020). "WT1 methylation was significantly associated with the risk of luminal A subtype of breast cancer with multivariable adjusted OR of 2.61 (95% CI: 1.18–5.74, P = 0.02), and PS adjusted OR of 2.62 (95% CI: 1.11–6.20, P = 0.03)." (PMID 32736539, 2020). "WT1 and its encoded protein are highly expressed in hematological malignancies and solid tumors such as breast cancer, lung cancer, pancreatic cancer, and prostate cancer." (PMID 32210734, 2020). "The results of the present study suggest that the hypermethylation of WT1 methylation in leukocytes is significantly associated with an increased risk of breast cancer." (PMID 32736539, 2020). "The nested case control study’s results showed a lower but still significant association between WT1 methylation and breast cancer risk, but the association between CA10 methylation and breast cancer risk was not statistically significant." (PMID 32736539, 2020). "This article focuses on the relationship between WT1 and breast cancer to comprehensively understand the effects and the underlying mechanisms of WT1 in breast cancer." (PMID 32210734, 2020). "The results showed that WT1 hypermethylation was associated with an increased risk of breast cancer, with an odds ratio (OR) of 3.07 [95% confidence interval (CI): 1.67–5.64, P < 0.01]." (PMID 32736539, 2020). "WT1 methylation was associated with breast cancer risk both in multivariable and PS adjusted methods with ORs of 2.42 (95% CI: 1.45–4.04, P < 0.01) and 3.07 (95% CI: 1.67–5.64, P < 0.01), respectively." (PMID 32736539, 2020). "WT1 methylation was also significantly associated with the risk of luminal B subtype breast cancer with ORs of 2.49 (95% CI: 1.13–5.51, P = 0.02) and 3.23 (95% CI: 1.34–7.80, P = 0.01) after multivariable and PS adjustment." (PMID 32736539, 2020). "Considerable evidence has implicated WT1 in the development, pathogenesis and therapy of breast cancer." (PMID 31860871, 2019). "WT1 has also been linked with in breast cancer malignant transformation, and its overexpression associated with reduced susceptibility to drug treatment." (PMID 31860871, 2019). "Obviously, we can see that NF1, BRCA1, FOXO1, PTEN, CAV1 and WT1 are linked with breast cancer genes in PPI network or pathway network." (PMID 31760937, 2019). "Our work is the first to demonstrate that the known association between WT1 expression in breast cancer and poor prognosis is potentially due to cancer-related epithelial-to-mesenchymal transition (EMT) and poor chemotherapy response." (PMID 28345629, 2017). "In conclusion, we demonstrate that cancer-related EMT and poor chemotherapy response are likely the main factors that explain why WT1 expression in breast cancer is usually associated with poor prognosis." (PMID 28345629, 2017). "It has been reported that methylation of WT1 is related to increased breast cancer risk." (PMID 38970307, 2024).
breast carcinoma (continued). "Furthermore, we used external data from an IPEC- Italy cohort (GEO-GSE51032) with a nested case control study design and found the significant association between WT1 methylation and breast cancer risk, with two CpG probes inside our sequence, with OR of 1.88." (PMID 32736539, 2020). "In the subgroup analyses, after PS adjustment, WT1 methylation was associated with breast cancer risk in both the younger (< 60-years-old) and older (≥60-years-old) groups, with ORs of 2.64 (95% CI: 1.31–5.32, P = 0.01) and 4.72 (95% CI: 1.31–16.97, P = 0.01), respectively." (PMID 32736539, 2020). "Using in vitro cell lines, clinical samples and publicly available gene expression datasets, we demonstrate that WT1 plays a role in regulating the epithelial-mesenchymal balance of breast cancer cells and that WT1-expressing tumours are mainly associated with a mesenchymal phenotype." (PMID 28345629, 2017). "High levels of WT1 are also associated with poor prognosis in both breast cancer and leukemia." (PMID 17634147, 2007). "Surprisingly, WT1 has been revealed to be overexpressed in several tumor tissues such as ovarian and breast cancer." (PMID 38944027, 2025). "To do so, we performed qPCR analyses on human melanoma and breast cancer cell lines undergoing LTHY adaptation using primer pairs that enable us to determine the expression of canonical WT1 or tWT1." (PMID 38977895, 2024). "The results showed that 5 genes, APOA5, CCDC28B, CCL5, SERPINA12, and WT1, were significantly overexpressed in breast cancer patients (P < 0.05)." (PMID 38676834, 2024). "TP63 and WT1 are also prominently expressed in squamous cell carcinoma, bladder cancer, breast cancer, and gastric cancer." (PMID 38794221, 2024). "Stable expression of Wt1 (−KTS) in the breast cancer cells significantly suppressed colony formation and cell division, whereas that of Wt1 (+KTS) did not." (PMID 36829196, 2023). "In breast cancer, HOXC11 couples with steroid receptor coactivator 1 to inhibit the expression of differentiation protein CD24 and apoptosis protein PRKC apoptosis WT1 regulator (PAWR) function from promoting the progression of breast cancer." (PMID 36823149, 2023). "In breast cancer data sets, high WT1 levels correlated with improved relapse-free survival and overall survival (GSE9893)." (PMID 36864480, 2023). "Numerous studies have demonstrated that WT1 plays an oncogenic role in various solid cancers including breast cancer, by promoting epithelial-to-mesenchymal transition and lowering chemotherapy efficacy." (PMID 36960071, 2023). "It had been reported that WT1 functions as an oncogene in non-small cell lung cancer and breast cancer." (PMID 36983712, 2023). "Despite the initial classification of WT1 as a suppressor gene, the overexpression of WT-1 in many cancers (breast cancer and acute leukemias) has led to its recognition as an oncogene." (PMID 35626018, 2022). "WT1, which also resides at 11p13, has been shown to promote a mesenchymal phenotype in breast cancer cells as well as to elicit resistance to taxane therapy." (PMID 35992833, 2022). "The expression level of WT1 also is an independent prognostic factor for a variety of cancers, including breast cancer, colorectal cancer and gynecological cancer, because of its superior predictive performance." (PMID 35123502, 2022). "In breast cancer, WT1 upregulates the expression of human epidermal growth factor receptor 2 (HER2), leading to estrogen-independent tumor growth and anti-estrogen resistance." (PMID 35465313, 2022). "WT1 in breast cancer cells has also been shown to contribute to an increased cell proliferation rate and a reduced apoptosis rate." (PMID 35123502, 2022).
breast carcinoma (continued). "In this study, we analyzed the expression of WT1 isoforms, ER, and Her2/neu in a long-term estrogen depletion in vitro model, to mimic the malignant progression of the breast cancer switch from estrogen-dependent to estrogen-independent growth." (PMID 34845427, 2021). "Initially, the characterization of the expression of the WT1 isoforms was carried out in the breast cancer cell lines MCF-7, BT-474, T47D, SKBR-3, MDA-MB-231, MDA-MB-453, and BT-20." (PMID 34845427, 2021). "Currently, it is not fully known how WT1 interacts with tumor markers used in the characterization of breast cancer, such as the estrogen receptor, progesterone receptor, and Her2/neu." (PMID 34845427, 2021). "The presence of WT1 is essential for breast cancer cell growth; however, it is still unclear what role it plays during the progression of breast cancer." (PMID 34845427, 2021). "Studies in breast cancer lines have demonstrated that WT1 expression is involved in the modulation of tumor marker expression." (PMID 34845427, 2021). "High expression of wild-type WT1 in breast cancer has been reported in more than 90%, and high levels of WT1 expression have been inversely associated with patient survival." (PMID 34845427, 2021). "Several clinical trials are currently being conducted to evaluate the effectiveness of CTAs, such as NY-ESO-1, MAGE, MSLN, PRAME, PSCA, ROR2 and WT1, as treatment targets in breast cancers and other solid tumours." (PMID 34359776, 2021). "For 31 hormone receptor (HR)+/HER2− breast cancers, there were two clusters: One with the co-occurrence of ATM, FGFR1, and WT1 frameshift mutations, and the other with JAK3 splice site and FGFR2 frameshift mutations." (PMID 34203389, 2021). "There are currently few studies where the 36-38 kDa WT1 isoform is analyzed, so it is important to carry out a characterization of the WT1 isoforms present in samples from breast cancer patients with variable tumor marker status." (PMID 34845427, 2021). "PKNOX1, and WT1 displayed higher mRNA expression in breast cancer tissues in comparison with normal breast tissues as well as their upregulation was associated with poor OS." (PMID 35186006, 2021). "WT1 methylation in the promoter and first exon region was shown to be associated with the silencing of WT1 mRNA expression in MCF-7 and MDA-MB-231 breast cancer cells." (PMID 32736539, 2020). "The P values for the interactions between age and the methylation of WT1 and CA10 on the risk of breast cancer were 0.40 and 0.73, respectively." (PMID 32736539, 2020). "After PS adjustment, we observed that methylation of WT1 was significantly elevated breast cancer risk by 2.07-fold, CA10 methylation was marginally associated with breast cancer risk with OR of 1.35." (PMID 32736539, 2020). "Much of the current research supports the premise that WT1 plays an oncogenic role in breast cancer, promoting cell proliferation and inhibiting apoptosis, but some other studies have different findings." (PMID 32210734, 2020). "WT1 has been reported to be significantly different methylated in the tissues of hepatocellular carcinoma, lung cancer and breast cancer." (PMID 32736539, 2020). "We also analyzed the combination and interaction of age and the methylation of WT1, CA10 on the risk of breast cancer." (PMID 32736539, 2020). "Our previous study showed that TGF-β can induce EMT by upregulating WT1 breast cancer cells, resulting in promoting proliferation, invasion, and migration of tumor cells." (PMID 32210734, 2020). "This is the first case-control study to investigate the associations between the methylation of WT1, CA10 in leukocyte DNA and breast cancer risk, and the risk of different molecular subtypes of breast cancer in a Chinese female population." (PMID 32736539, 2020). "WT1 can increase the malignancy of breast cancer, leading to poor prognosis in patients with high WT1 expression." (PMID 32210734, 2020).
breast carcinoma (continued). "In this study, we investigated the associations between the methylation of WT1, CA10 in peripheral blood leukocyte DNA and breast cancer risk." (PMID 32736539, 2020). "For example, WT1 expression levels in breast cancers were significantly higher than in control tissue." (PMID 31860871, 2019). "Overexpression of WT1 induces a significant increase in the abundance of endogenous MYC protein in breast cancer cells, whereas a WT1/BASP1 complex represses the MYC promoter." (PMID 31058089, 2019). "More detailed analysis of WT1 expression in breast cancer samples and matched controls was performed using double Immunofluorescence." (PMID 30374123, 2018). "The sub-analysis of WT1 expression in endothelial cells versus histopathological grade clearly shows that as breast carcinomas become undifferentiated vascular WT1 expression decreases." (PMID 30374123, 2018). "Comparison with control tissues, and stratification of the tumours, suggests that an improved understanding of the role of WT1 in the healthy breast and in breast cancer is required to aid the development of therapies targeting WT1 in this condition." (PMID 30374123, 2018). "The Wilms’ tumour protein (WT1), which influences tumour development and angiogenesis, is a promising therapeutic target in breast cancer." (PMID 30374123, 2018). "Quantification demonstrated that the total number of WT1-positive cells was higher in the human breast cancer samples (n = 57) than in matched controls." (PMID 30374123, 2018). "Clearly, a better understanding of the relationship between WT1 and breast cancer is required to inform the development of immunotherapy for targeting WT-positive tumour cells in this condition." (PMID 30374123, 2018). "Future studies should determine the pattern of WT1 isoform expression in sub-types of human breast cancer." (PMID 30374123, 2018). "Expression of WT1 is increased in breast cancers but this is not limited to the vascular compartment." (PMID 30374123, 2018). "The results obtained show clearly that WT1 is expressed in the endothelial cells, and also in smooth muscle and epithelial cells, of tumour-free mammary tissue from patients with breast cancer." (PMID 30374123, 2018). "WT1 immunopositivity was identified in several cell types both in control breast tissue and in breast cancers." (PMID 30374123, 2018). "WT1 was identified in endothelial (and epithelial and smooth muscle) cells in tumours and tumour-free tissues (controls) from patients and mice with breast cancer." (PMID 30374123, 2018). "This is consistent with the WT1 upregulation identified in the human breast cancer samples versus matched controls." (PMID 30374123, 2018). "WT1 expression and vascular density were quantified by immunohistochemical analysis of human (n = 57) and murine breast cancers." (PMID 30374123, 2018). "The enforced WT1 expression successfully, albeit partially, reversed the anti-proliferative, anti-migration, and anti-invasion effects of miR-193a on breast cancer cells, although there are many targets of miR-193a." (PMID 29016617, 2017). "Our results reveal that miR-193a-WT1 interaction plays an important role in breast cancer metastasis, and suggest that restoring miR-193a expression is a therapeutic strategy in breast cancer." (PMID 29016617, 2017). "As a whole, this study has shown that WT1 can disrupt the epithelial-mesenchymal balance of breast cancer lines in opposite ways, depending on the baseline characteristics of the cells." (PMID 28345629, 2017). "In order to overcome these limitations, we have performed a more detailed and comprehensive analysis of WT1 expression in breast cancer using different approaches (in vivo, in vitro and in silico)." (PMID 28345629, 2017). "In this study, we have partly elucidated miR-193a regulation of WT1 in breast cancer, where the mechanism of miR-193a downregulation during carcinogenesis can accelerate cell growth and promote cancer cell diffusion." (PMID 29016617, 2017).
breast carcinoma (continued). "In order to assess if WT1 knockdown affects the motility of breast cancer cells, we performed migration and invasion assays." (PMID 28345629, 2017). "An RNAi-based gene knockdown strategy was used to investigate the functional role of WT1 in breast cancer cells." (PMID 28345629, 2017). "In the early stage of breast cancer development, DNA hypermethylation occurs in the WT1 promoter and leads to the low WT1 expression in breast cancer." (PMID 29016617, 2017). "Here we provide a complete study of WT1 expression across different breast cancer subtypes as well as isoform specific expression analysis." (PMID 28345629, 2017). "qRT-PCR was conducted on 25 pairs of human breast cancer tissues and their adjacent non-cancerous tissues to validate the correlation between miR-193a and endogenous WT1 expression in breast cancer." (PMID 29016617, 2017). "Available literature suggests an oncogenic nature of WT1 and has shown its overexpression in various tumors and tumor cell lines, especially in breast cancer cells and melanoma." (PMID 28458685, 2017). "In breast cancer, higher WT1 expression is associated with higher histological stage and worse prognosis, and WT1 acts as an oncogene in breast cancer progression." (PMID 29016617, 2017). "We found that miR-193a overexpression inhibited the migration and invasion of breast cancer cells by modulating WT1 expression." (PMID 29016617, 2017). "miR-193a acts as a tumor suppressor by targeting WT1, thereby suppressing breast cancer growth and metastasis." (PMID 29016617, 2017). "When we perturb the expression levels of WT1, either by knocking it down or over-expressing it, the breast cancer cells show a disruption of their epithelial-mesenchymal balance, which seems to be dependent on their baseline characteristics." (PMID 28345629, 2017). "WT1 plays an oncogenic role in BC and is expressed in approximately 33% (range: 3–48.5%) of malignant breast tumors." (PMID 28176175, 2017). "Less than 10% of primary breast cancer cases are positive for WT1, with weak and patchy WT1 expression." (PMID 27047697, 2016). "Approximately 15% of breast primary cancers of the papillary mucinous subtype are positive for WT1, an independent marker for mesothelioma." (PMID 25849448, 2015). "In healthy endometrium progesterone induces WT1 isoforms which in turn leads to the differentiation into decidua, while in breast cancer cells progesterone analogs reduce WT1 expression thereby inducing differentiation." (PMID 24955840, 2014). "In osteosarcoma, soft tissue sarcomas, and breast cancer patients, WT1 expression confers a poor prognosis." (PMID 24810959, 2014). "PRL positively interacted with E2 to further elevate several transcripts encoding growth and progression factors for breast cancer, including AREG, EREG, PTHrP and WT1." (PMID 23758962, 2013). "It was also reported that WT1 is required for inhibition of apoptosis in breast cancer and rhabdoid cancer by decreasing Bcl-2 mRNA and protein levels; however, other reports indicated that WT1 negatively regulated the Bcl-2 promoter in the prostate cell line." (PMID 23936312, 2013). "The most frequently hypermethylated genes (MSH6, CDH13, PAX5, PAX6 and WT1) were similar for male and female breast cancer." (PMID 22765268, 2012). "Recent studies have demonstrated high expression of WT1 in bone and soft tissue sarcomas, breast cancer and lung cancer." (PMID 20842112, 2010). "We were also able to identify several genes, such as CDKN2A, PCDHGB6, and WT1 well known to be methylated and transcriptionally silent in breast cancer." (PMID 19250546, 2009). "We then go on to demonstrate in WT1-expressing breast cancer cells that WT1–ZF behaves as a dominant negative and inhibits cell growth and survival." (PMID 17634147, 2007). "Our observations strongly argue that the WT1–ZF plasmid behaves as a dominant-negative regulator of the endogenous WT1 in breast cancer cells." (PMID 17634147, 2007).